RLIMP2 (ring finger protein, LIM domain interacting pseudogene 2)
Gene: Processed pseudogene on chromosome 1 (113,125,321 to 113,126,883, reverse strand). Ensembl gene ENSG00000237278.
Diseases named in the same sentence as RLIMP2 in open-access papers:
RLIMP2 is named in the same sentence as 3 diseases in open-access papers, as found by Europe PMC text mining. Sharing a sentence is not in itself a finding about the gene and the disease.
RLIMP2 shares sentences with these, for which no sentence is quoted: autoimmune disease (1 paper); hypothyroidism (1); ulcerative colitis (1).